GSTP1 (glutathione S-transferase pi 1)
Diseases named in the same sentence as GSTP1 in open-access papers (continued):
Sharing a sentence is not in itself a finding about the gene and the disease.
tumor (continued). "On the other hand, except metabolism, the derived genes are also associated with distinct modes of tumor physiology in CRC, such as detoxification (GSTP1), metastasis (KIT), immunomodulation & stem cell renewal (CD44) and ER stress (CCT7)." (PMID 30809322, 2019). "Detectable levels of urinary GSTP1-1, deriving from desquamation of the tumor, have been addressed in only one study as a potential urinary marker." (PMID 31357662, 2019). "In vivo tumorigenesis model, we found that overexpression of GSTP1 significantly rescued FBX8-induced suppression of tumor growth (P < 0.01)." (PMID 31024008, 2019). "One such example of DNA hypermethylation occurs with GSTP1, a detoxifying enzyme with tumor suppressive activity." (PMID 30875962, 2019). "EA is active against human tumor cells in particular through its inhibitory activity on GSTP1-1 by covalent binding of the GSH-EA complex." (PMID 29362397, 2018). "In particular, GSTP1-1 is able to protect the tumor cells from apoptosis signals by inhibiting c-Jun N-terminal kinase (JNK)—a member of the MAPK pathway—non-catalytically, by direct protein–protein association." (PMID 29362397, 2018). "Higher GSTP1 levels in tumor tissues indicated a better OS and DFS for HCC patients enrolled in our study." (PMID 29507666, 2018). "Our immunohistochemical analysis demonstrated that GSTP1 is expressed in normal samples, showing strong or moderate expression and in most of the tumor cases, in which the expression was varying between strong, moderate, and weak." (PMID 30043549, 2018). "The tumor volumes of GSTP1-transfected mice at 18 days, 21 days, and 24 days were reduced compared with those in the control group (P < 0.05)." (PMID 29507666, 2018). "GSTP1 levels correlated negatively with tumor size and serum alpha-fetoprotein (AFP) in HCC patients, and higher GSTP1 levels associated with longer overall survival (OS) and disease-free survival (DFS)." (PMID 29507666, 2018). "GSTP1 mRNA was down-regulated in HCC tissues compared with adjacent non-tumor liver tissues (P < 0.0001 for GEO and P = 0.0003 for TCGA)." (PMID 29507666, 2018). "Previous GSTP1 studies have reached contradicting conclusions, so we investigated GSTP1’s effects on tumor progression and prognosis in HCC." (PMID 29507666, 2018). "The treatment of these tumors with morpholinos against GSTM3 and GSTP1 resulted in a decrease of tumor volume by 10- and 6-fold, respectively." (PMID 29774096, 2018). "The aberrant methylation of GSTP1 has been shown to be associated with HCC progression, and to be more frequent in tumours characterized by capsular invasion and metastasis." (PMID 29597259, 2018). "HCC patients with lower AFP and smaller tumor size were more likely to have higher GSTP1, which was correlated to better OS and DFS." (PMID 29507666, 2018). "Cluster A contained 12 tumours and was characterised by high GSTP1 methylation and MAL methylation and relatively lower RASSF1A methylation." (PMID 28893223, 2017). "NBDHEX and MC3181 inhibit glutathione transferase P1-1 (GSTP1-1), and disrupt the GSTP1-1/JNK1 and GSTP1-1/TRAF2 complexes, thereby causing prolonged tumor cell cycle arrest and apoptosis." (PMID 28107182, 2017). "Six tumor-associated genes (RASSF1A, APC, BVES, TIMP3, GSTP1, and HOXA9) were selected as candidates." (PMID 28951629, 2017). "In our tumor tissues, we identified the sporadic expression of 9 detox proteins (encoded by seven genes), namely: SODC, CATA, PRDX2, PRDX6, GSTP1, ALDR and AK1BA." (PMID 28686225, 2017). "Our meta-analysis indicated that the heterogeneity was not contributed by geographical populations, except RASSF1A and GSTP1 between HCC tumor tissues and normal tissues in Japan and America respectively." (PMID 27835605, 2016). "GSTP1 seems to be involved in different tumor types, due to its role in detoxification of exogenous substances and regulation of cell cycle, and its overexpression is often associated with drug resistance." (PMID 27594734, 2016).
tumor (continued). "In line with previous studies, we found GSTP1 methylation in 91.1% of tumor tissues and in 5.4% of adjacent healthy tissues." (PMID 27594734, 2016). "We found that there was significant difference in RASSF1A and GSTP1 between HCC tumor tissues and normal tissues in Japan (p = 0.041) and America (p = 0.021) respectively." (PMID 27835605, 2016). "With the exception of GSTP1, the methylation status was significantly lower in tumor-distant tissues than in tumors." (PMID 26370119, 2015). "Glutathione S-transferase P1 (GSTP1) has been reported to function as a tumor suppressor gene in various types of human cancers." (PMID 26585467, 2015). "This makes thiazolides an interesting novel class of anti-tumor drugs specifically targeting tumors with elevated levels of GSTs, and GSTP1-1 an Achilles' heel for the potential therapeutic action of thiazolides." (PMID 26043078, 2015). "Since PR expression has a prognotic value and is related to favourable prognosis, further investigation is needed to clarify the effect of GSTP1 on tumor characteristics." (PMID 25648141, 2015). "We studied the association between tumor pathology and the expression profile of seven phase I and II drug metabolizing genes (CYP1A1, CYP1B1, ALDH3A1, AOX1, GSTP1, GSTT1 and GSTM3) and some of their proteins." (PMID 26580399, 2015). "In this study, we examined methylation patterns of ten tumor-associated genes (RASSF1A, GSTP1, RIZ1, SOCS1, TNFRSF10C, hTERT, NRG1, CLU, miR-203, miR-663) and of the LINE-1 repetitive element in 45 HCC and 17 matching non-tumor livers." (PMID 25889455, 2015). "Other natural compounds, like genistein and lycopene, can alter DNA methylation of the glutathione S transferase p1 (GSTP1) tumor suppressor gene." (PMID 25869442, 2015). "In prostate, but also breast, endometrial and hepatocellular carcinomas, another early tumor marker is GSTP1 promoter methylation which is detected at various percentages of clinical samples." (PMID 25157234, 2014). "Frequently methylated genes in HCC such as P16/CDKN2A, CDH1 and GSTP1 were also found to be similarly hypermethylated in our tumor samples." (PMID 25093504, 2014). "Important question is when the promoter hypermethylation of the GSTP1 gene starts to play a role in tumor progression?" (PMID 24093668, 2013). "A corresponding report stated that there is a correlation between the expression of GSTP1 proteins in tumor tissues and prognosis in ovarian cancer." (PMID 24202339, 2013). "Methylation analysis of GSTP1, P14 and P21 in primary tumor tissue showed slightly higher methylation proportion in comparison to the matched normal tissue, however, the differences were not significant." (PMID 22695536, 2012). "Among the most strongly repressed proteins, glutathione-S-transferase pi (GSTP1) constituted an interesting target gene, since it represents an important factor fulfilling protective and detoxifying functions in tumor cells." (PMID 22532850, 2012). "GSTP1 is considered to act as a tumor-suppressor gene, leading to tumor growth when it is inactivated." (PMID 23226781, 2012). "The breast is an important organ of the body which is continuously exposed to these steroids and it is therefore highly likely that estrogens act as endogenous tumor initiators in the breast tissue when GSTP1 is inactivated by promoter methylation." (PMID 23226781, 2012). "In exacting, GSTP1 is involved in the regulation of cell proliferation, apoptosis, stress response, phase II metabolism, oncogenesis, tumour progression and drug resistance." (PMID 22272830, 2012). "The analyses showed significant correlation between higher methylation level of GSTP1 and increasing the histological grade in the primary tumor tissue (Spearman's rho test; P < 0.05)." (PMID 22695536, 2012). "The GSTP1 gene was significantly hypermethylated in tumor tissue and P21 gene was mostly hypermethylated in serum samples compared to the normal tissue." (PMID 21283676, 2011).
tumor (continued). "Another advantage of using GSTP1 as a marker of DNMTi efficacy is that it can be easily measured in a patient's serum or circulating tumor cells which will facilitate its use as a biomarker in future clinical trials." (PMID 21980513, 2011). "Herein, we analyzed the presence of GSTP1/JNK complexes in specimens of tumor tissue of the urinary bladder obtained from 20 patients with TCC after radical cystectomy, as well as in the 5637 TCC cell line." (PMID 21637416, 2010). "Identification of genes with subtype-specific methylation revealed that, for example, RASSF1 and GSTP1 were specifically methylated in lumB tumours and unmethylated in basal-like tumours." (PMID 20565864, 2010). "Our group has previously found that GSTP1 methylation correlates with increased tumor size and increased likelihood of sentinel lymph node metastases." (PMID 18485221, 2008). "The GSTP1 isoenzyme is highly expressed in the mammary epithelium, both in normal and in tumor cells." (PMID 18542066, 2008). "Hypermethylation of GSTP1 was identified in 75/79 (94.94%) tumours, 10/14 (71.43%) HGPIN, 5/39 (12.82%) histologically normal prostate samples and 4/37 (10.81%) BPH." (PMID 17453001, 2007). "In a pilot study we analyzed tumor tissue from a highly selective cohort of patients before and after long-term neoadjuvant hormonal therapy for the presence of GSTP1-HM by methylation specific PCR (MSP)." (PMID 16803634, 2006). "For example, the endothelium in the tumor area of patient 7 demonstrated 100% methylation at GSTP1, while the tumor epithelium only showed 10% methylation." (PMID 16512911, 2006). "Comparing GSTP1 and RARβ2 promoter methylation data, we show that 100% and 88% methylation is detected, respectively, in the tumor areas, both in epithelium and endothelium." (PMID 16512911, 2006). "In particular, GSTP1 and RARβ2 have been found to be highly methylated within the tumor epithelium of the prostate." (PMID 16512911, 2006). "A possible involvement of GSTP1 in etoposide resistance of human tumours was previously suggested by studies showing either an elevated GSTP1 in many cell lines selected in the drug or a significantly influenced resistance by single transfection of GSTP1." (PMID 15999103, 2005). "Additionally, a significant correlation between GSTP1 hypermethylation and poor clinical outcomes, such as advanced tumor stage, recurrence, and reduced overall survival, was observed (OR = 2.56, 95% CI: 1.80–3.64)." (PMID 40051701, 2025). "There is considerable heterogeneity in the methodologies used to assess GSTP1 hypermethylation, including differences in the biological samples analyzed (e.g., tumor tissue vs. blood) and the detection techniques (e.g., PCR-based methods vs. methylation arrays)." (PMID 40051701, 2025). "In the context of HCC, epigenetic therapies aimed at reversing GSTP1 hypermethylation could enhance the cellular detoxification capacity and reduce tumor progression by reactivating the silenced GSTP1 gene." (PMID 40051701, 2025). "In hepatocellular carcinoma, PCSK9 exhibits dual roles: it can promote tumor growth by inhibiting apoptosis through the Bax/Bcl-2/Caspase pathway and also acts as a tumor suppressor by interacting with GSTP1 and inhibiting the c-Jun n-terminal kinase signaling pathway." (PMID 40764605, 2025). "In the case of GSTP1, its inactivation through hypermethylation can diminish the cell’s capacity to detoxify carcinogens, thus facilitating the accumulation of genetic damage and tumor development." (PMID 40051701, 2025). "The silencing of GSTP1 through hypermethylation may lead to an impaired ability to detoxify carcinogens and protect cells from oxidative stress, which can contribute to tumor progression, metastasis, and resistance to chemotherapy." (PMID 40051701, 2025). "In HCC, such strategies could potentially reactivate GSTP1 and enhance the cellular defense against carcinogens, thereby inhibiting tumor growth and progression." (PMID 40051701, 2025).
tumor (continued). "Other assays such as SelectMDx and ConfirmMDx detect DNA hypermethylation patterns in tumor suppressor genes (e.g., GSTP1, RASSF1), which are influenced by the availability of metabolic cofactors like S-adenosylmethionine (SAM) and acetyl-CoA—central intermediates in epigenetic regulation." (PMID 40649790, 2025). "Additionally, evidence suggests that the S-HDAg can bind specifically to the transcript of the glutathione S-transferase P1 (GSTP1) tumor suppressor gene, leading to a significant reduction in GSTP1 protein production." (PMID 38787214, 2024). "Indeed, investigations in TCGA PRAD data show correlation between GSTP1 methylation and pathology measures of tumour purity." (PMID 39744075, 2024). "Related studies have indicated that GSTP1 inactivation inhibits tumor cells from evading ferroptosis, leading to tumor growth, suggesting that piR-31470 may suppress ferroptosis through the inactivation of GSTP1." (PMID 37686142, 2023). "Thus, GSTP1 is a lactate–binding protein, the function of which is probably modulated in response to lactic acid levels that constitute, at least in part, a tumor metabolic micro-environment." (PMID 37491277, 2023). "Interestingly BARD1, CTSB, and GSTP1 were all highly expressed in tumor samples from the TCGA dataset." (PMID 37727789, 2023). "As 1 is active on human tumor cells by inhibiting GSTP1-1, this may suggest that GST could be a relevant target of 1 in P. falciparum." (PMID 35215282, 2022). "GSTP1 is involved in the drug resistance of tumor cells, including BC." (PMID 35027621, 2022). "In addition, it has been surprisingly found that GSTP1 is involved in tumor development through ferroptosis pathway." (PMID 36589232, 2022). "Those prove that GSTP1 is an important factor in tumor cells for drug resistance." (PMID 35509845, 2022). "The potential role of GSTP1 in ferroptosis pathway for tumor treatment." (PMID 36589232, 2022). "Accordingly, a high level of GSTP1 in circulating EVs may be an indication of a drug-resistant profile and could be used as a drug resistance predictive marker as already demonstrated for the expression of GSTP1 on tumor cells." (PMID 36091133, 2022). "Indeed, tumours often express high levels of GST (particularly GSTP1), and GSTs are frequently overexpressed in multidrug-resistant cells." (PMID 33640700, 2021). "Therefore, research needs to further explore the role of GSTP1 in tumor tissue after radiotherapy, so that clinic can make individual treatment for patients to reduce the occurrence of RILI." (PMID 34238333, 2021). "GSTP1 is highly expressed in a variety of tumor tissues and can be used as a biomarker in tumors." (PMID 34238333, 2021). "Recently, it has been shown that neoplastic transformation by silencing GSTP1 tumor suppressor gene function might be mediated by activation of c-myc, whereas the significant protective effect was shown after GSTP1 overexpression in PC in vitro and in vivo." (PMID 33937322, 2021). "Furthermore, our results show that GSTP1 knockdown PDAC cells generated significantly smaller tumors (p < 0.05) with a 50–80% reduction in tumor weight compared to the control." (PMID 32526885, 2020). "These genetic alterations include hypermethylation of the Glutathione S-transferase P1 (GSTP1) promoter, the stimulation of the proto-oncogene Myc, and deletions of regions protecting recognized tumor suppressors on chromosome 10q23 such as phosphatase and tensin homolog (PTEN)." (PMID 32906694, 2020). "To explain the dramatic reduction in tumor size in GSTP1 knockdown cells, we evaluated the expression of the nuclear proliferation marker Ki-67 and the apoptotic marker cleaved caspase-3 by immunohistochemistry in mouse tumor tissues." (PMID 32526885, 2020).
tumor (continued). "Hence, these findings suggested that NQO1 and GSTP1 were upregulated in the tumor tissues of GBM patients, and their expression was correlated." (PMID 33087132, 2020). "Also, GSTP1 is a gene that is related to DNA repair, and keeps DNA from an impairment, controls detoxification and metabolism, so preventing tumor incidence." (PMID 32334487, 2020). "GSTP1 methylation testing in non-tumor tissue could thus potentially be combined with tests with high sensitivity, such as targeted biopsy after mp-MRI, to improve overall diagnostic accuracy." (PMID 31666119, 2019). "In conclusion, GSTP1 mRNA levels in the tumor tissues did not exhibit a significant association with the clinicopathological features of the patients but only mediating resistance of tumor cells to cisplatin." (PMID 31357662, 2019). "At 24 months of follow-up, patients with advanced tumours (26.3% vs. 83.3%, p = 0.02) and patients with the GSTP1 ValVal genotype (0.0% vs. 31.7%, p = 0.047) had shorter event-free survival (EFS) than those with localised tumours and those harbouring the GSTP1 IleVal or ValVal genotype." (PMID 31249357, 2019). "In tumor cells, kinase pathways are dysregulated, and so the cells may attempt to compensate by enhancing expression of GSTP1-1 to control kinase activity." (PMID 31357662, 2019). "In mice models of tumor growth and orthotopic metastasis established by subcutaneous and injected into serous of cecum with CRC cells, we found that GSTP1 enhanced primary tumor growth (P < 0.01) and significantly increased the number of metastatic liver nodules in mice (P < 0.05)." (PMID 31024008, 2019). "Free radicals produced by CDDP that are not detoxified due to the lack of GSTP1 are likely to induce new mutations in residual tumour cells, thereby facilitating survival and proliferation of the tumour cells." (PMID 31249357, 2019). "Tumor mass was lower in the GSTP1 overexpression group at the time of harvest (P < 0.01)." (PMID 29507666, 2018). "In addition, larger alterations in DNA methylation from normal to tumor tissue have been reported for validated PrCa TSGs as GSTP1." (PMID 29744254, 2018). "Drug resistance observed in tumor tissues have been associated with the overexpression of GSTP1, which effectively blocks JNK signaling pathways while specific inhibitors of GSTP1 induce activation of JNK." (PMID 29720942, 2018). "In summary, GSTP1 mRNA was down-regulated in tumor compared with para-tumor liver tissues in HCC." (PMID 29507666, 2018). "Furthermore, GSTM3 and GSTP1 knockdown showed that evasion of apoptosis was affected, and tumor proliferation was significantly reduced." (PMID 29774096, 2018). "In addition, the positive rate of GSTP1 protein expression was significantly different in clinical stages (CSs): the lower the CS of the tumor, the higher the positive expression rate of the GSTP1 protein (P=0.049)." (PMID 28978147, 2017). "Thus, after univariate analysis, the variables significantly correlated with GSTP1 protein expression were tumor size and clinical stage." (PMID 28978147, 2017). "Another potential non-invasive biomarker for PCa is represented by the presence of methylated GSTP1 DNA in plasma and serum of PCa patients; this epigenetic status was associated with prognosis, advanced AJCC tumor stage, PSA recurrence after surgery and response to chemotherapy." (PMID 28061466, 2017). "GSTP1 is overexpressed in tumors and tumor cells resistant to several anticancer drugs." (PMID 28254657, 2017). "GSTP1-1 is overexpressed in tumor cells, suggesting that it may contribute to their drug resistance." (PMID 27487128, 2016). "Dysregulation of GSTP1 methylation is frequent in different tumor types." (PMID 27594734, 2016). "The GSTP1 gene is a tumor suppressor gene and locus on chromosome 11q13." (PMID 26585467, 2015). "Tumor tissues and blood samples were used to detect the methylation status of GSTP1 promoter." (PMID 26585467, 2015).